HMGA1 (high mobility group AT-hook 1)
Diseases named in the same sentence as HMGA1 in open-access papers (continued):
Sharing a sentence is not in itself a finding about the gene and the disease.
pancreatic cancer (continued). "Interestingly, high expression levels of Hmga1 have been associated with premature EMT and prolonged stemness in several cancers of the pancreas, breast, lung, and ovaries." (PMID 32965216, 2020). "Our findings reveal that HMGA1 expression is significantly higher in PDAC tissues, especially in patients with advanced stages of pancreatic cancer, than in healthy ones." (PMID 41145488, 2025). "We next knocked down c-Myc in pancreatic cancer cells, which blocked the GAA-induced expression of HMGA1 and HMGA2." (PMID 37370109, 2023). "In another report of pancreatic cancer, CERS6-AS1 sequesters miR-15a-5p, which induces the expression of FGFR1 and HMGA1, two key oncogenes, promoting pancreatic cancer proliferation and migration." (PMID 35927226, 2022). "In the study of pancreatic cancer, it was found that miR-138-5p was down-regulated in PANC-1 cells, and silencing of miR-138-5p induced the increase of CCAT1 and HMGA1 expression." (PMID 34660700, 2021). "We previously demonstrated that human pancreatic carcinoma expresses high HMGA1 levels, indicating that both HMGA2 and HMGA1 are overexpressed in this lesion." (PMID 14647145, 2003). "Public databases show that HMGA1 protein is highly expressed in many cancers, including hepatocellular carcinoma (HCC), lung adenocarcinoma, and pancreatic cancer, and patients with high HMGA1 expression have a worse prognosis than those with low HMGA1 expression." (PMID 40288645, 2025). "Furthermore, the expression pattern of HMGA1 and FOXM1 showed a significant strong positive correlation in most type of cancers, especially lung adenocarcinoma, pancreatic cancer and liver cancer." (PMID 37240870, 2023).
cervical cancer (26 papers, 2019 to 2025). A primary or metastatic malignant neoplasm involving the cervix. "HMGA1 induces tumor growth via regulation of cell cycle as well as facilitates migrated and invasive capacities in cervical cancer." (PMID 37710236, 2023). "excavated that miR-142-3p functioned as a tumor-suppressive miRNA through modulating the expression of HMGA1, A2, B1, and B3 in human cervical cancer." (PMID 37538797, 2023). "HMGA1 was first discovered in aggressive cervical cancer cells and is involved in the pathogenesis of various malignant cancers." (PMID 39282156, 2023). "Akhtar and Rajeshwari (2017) have reported that triplex formation selectively inhibits high-mobility group A1 proteins (HMGA1) expression and induce apoptosis in human cervical cancer." (PMID 36134025, 2022). "Has_circ_0000511 is overexpressed in cervical cancer and regulates the miR-296-5p/HMGA1 signalling pathway axis to inhibit HeLa and SiHa proliferation and invasion." (PMID 35155186, 2021). "HMGA1 exacerbates cervical cancer growth via regulating cell cycle and migration/invasion capacity through targeting miR-221/222." (PMID 33407473, 2021). "To verify it, we also investigated the expression of HMGA1 in different cervical cancer cells and found that the expression level of HMGA1 in SiHa and HeLa cells was higher than that in H8 and C-33A cells." (PMID 34136582, 2021). "Previously, miR-221 is targeted and regulated by transcriptional factor HMGA1 during cervical cancer." (PMID 32477928, 2020). "Studies show that HMGA1 is an oncoprotein in cervical cancer; however, the molecular underpinnings of malignant progression remain poorly understood." (PMID 30614613, 2019). "Compared with IMRT alone, the combination of IMRT and MWD more effectively downregulates tumor markers and the levels of TGF-β, bEGF, and HMGA1 in patients with cervical cancer, improves tumor control effectiveness and patient QoL, and facilitates the improvement of disease prognosis." (PMID 40636372, 2025). "In addition, HMGA1 overexpression enhances tumor growth and accelerates cell migration and invasion in cervical cancer cell lines." (PMID 36011023, 2022). "For example, miR-125b regulated HMGA1 and inhibited cervical cancer progression." (PMID 35187068, 2021). "The study indicated that the hsa_circ_0000511/hsa-miR-296-5p/HMGA1 axis may play an important role in the development of cervical cancer." (PMID 34136582, 2021). "Studies reported that HMGA1 regulated miR-222 in cervical cancer cells." (PMID 32123163, 2020). "Similarly, we had reported that HMGA1 exacerbates tumor growth and accelerates migration/invasion of cervical cancer, suggesting that HMGA1 might be a target oncoprotein." (PMID 36479041, 2022). "HMGA1, up-regulated in NOMO1-KO cells, is overexpressed in cervical cancer tissues and is positively correlated with lymph node metastasis and advanced clinical stage." (PMID 36011023, 2022). "In cervical cancer, FOXD3-AS1 directly interacts with miR-296-5p and elevates HMGA1 levels mediated by transcription factor SP1, thereby enhancing the proliferative ability of HeLa and C33A cells." (PMID 35280790, 2022). "Compared to IMRT alone, the combination of IMRT and MWD treatment for cervical cancer patients can significantly downregulate tumor markers and levels of TGF-β, bEGF, and HMGA1, increase tumor control effectiveness and patient QoL, and improve disease prognosis." (PMID 40636372, 2025). "Similarly, in cervical cancer HeLa and C33A cells, FOXD3-AS1 acts as an oncogene and competitively binds to miR-296-5p, which dramatically increases the levels of HMGA1, thus restraining tumor cells apoptosis." (PMID 35280790, 2022). "In cervical cancer HeLa and C33A cells, FOXD3-AS1 accelerates invasion and migration by competitively binding to miR-128-3p and elevating LIMK1 expression as well as through clearing miR-296-5p and subsequently increasing HMGA1 levels." (PMID 35280790, 2022).
cervical cancer (continued). "Thus, miR-142-3p directly targets HMGA1, HMGA2, HMGB1, and HMGB3, inhibiting them through reduction of cell viability, colony formation, migration, and invasion, as well as induction of apoptosis of tumor cells, particularly cervical cancer cells." (PMID 39062899, 2024).
hepatocellular carcinoma (24 papers, 2009 to 2025). A malignant tumor that arises from hepatocytes. "Lastly, High mobility group A1 (HMGA1) demonstrates elevated expression in various malignant tumors, including pancreatic ductal adenocarcinoma and hepatocellular carcinoma, suggesting its role in enhancing cancer cell invasiveness 34-36." (PMID 39744172, 2025). "The prognostic value of the HMGA1 expression level was demonstrated in some neoplasms, e.g., pancreatic, gastric, endometrial, hepatocellular cancer, but the knowledge about its role in non-small cell lung cancer (NSCLC) is still limited." (PMID 35948739, 2022). "For example, it was reported that the expression of HMGA1 was upregulated in hepatocellular carcinoma and related to prognosis." (PMID 36479041, 2022). "To date, except for MCL1 which has been proven by us and other literature studying hepatocellular carcinoma, among the validated miR-26a targets, HMGA1, PTEN, EZH2, MITF, DNMT3B, TGF-beta, and Ezh2 have been demonstrated to regulate chemoresistance." (PMID 33816494, 2021). "In fact, reversal of HMGA1-mediated immunosuppression could improve hepatocellular carcinoma therapy." (PMID 38329444, 2024). "However, ectopic expression of HMGA1 in hepatocellular carcinoma blocks the G0/G1 to S transition, indicating a cell-type-dependent function of HMGA1." (PMID 37240870, 2023). "KIFC1 activation contributes to HCC development of hepatocellular carcinoma by modulating the transcriptional activity of HMGA1." (PMID 38457554, 2024). "However, the specific role of HMGA1 in hepatocellular carcinoma (HCC) and relevant influencing approaches in tumor immunity remain unclear." (PMID 36705364, 2023).
type 2 diabetes (24 papers, 2008 to 2024). "The BMI-associated variant rs7084454 (intronic to MLLT10) was shared by substantial clusters for PCOS, endometriosis, and UF, while rs114760566 (mapped to HMGA1, associated with type 2 diabetes and multiple lipomatosis) was shared by endometriosis and UF." (PMID 35104295, 2022). "In particular, cardiac hypertrophy and type 2 diabetes have been found in Hmga1-null mice, underlining the HMGA1 key role in cardiomyocytic development and regulation of the insulin pathway." (PMID 31487906, 2019). "More recently, the credibility of an association between the HMGA1 rs139876191 variant and type 2 diabetes was confirmed also in a transethnic meta-analysis that included all available published articles examining this association in different populations." (PMID 30034366, 2018). "Herein, we evaluated the association of the HMGA1 rs139876191 with DR in an Italian cohort of type 2 diabetic patients." (PMID 27991577, 2016). "Results revealed that patients with type 2 diabetes, who were carriers of the HMGA1 rs139876191 variant had a significantly lower risk of developing PDR, compared to non-carrier diabetic patients." (PMID 27991577, 2016). "Targeting HMGA1 function would also be an interesting scenario in other diseases HMGA1 has directly been implicated in, such as cardiac hypertrophy, sepsis, type-2 diabetes, and the inflammatory response." (PMID 26117853, 2015). "The high-mobility group A1 (HMGA1) gene has been previously identified as a potential novel candidate gene for susceptibility to insulin resistance and type 2 diabetes (T2D) mellitus." (PMID 26296198, 2015). "Previously, we reported that defects in HMGA1 caused decreased insulin receptor expression and increased susceptibility to type 2 diabetes mellitus in humans and mice." (PMID 25628604, 2014). "Recently, the high-mobility group A1 gene (HMGA1) variant IVS5-13insC has been associated with type 2 diabetes, but reported associations are inconsistent and data are lacking in Hispanic and African American populations." (PMID 23302499, 2013). "Functional studies and replication of these associations are needed to better define the potential role of HMGA1 variants in predicting type 2 diabetes development." (PMID 23302499, 2013). "We tested the association of HMGA1 IVS5-13insC with type 2 diabetes in an ethnically diverse population from the INternational VErapamil SR-Trandolapril STudy (INVEST)." (PMID 23302499, 2013). "Consistently, lack of HMGA1 causes insulin resistance and diabetes in humans and mice, while variations in the HMGA1 gene are associated with the risk of type 2 diabetes and metabolic syndrome, two highly prevalent diseases that share insulin resistance as a common pathogenetic mechanism." (PMID 30034366, 2018). "Also, evidence has been provided implicating the HMGA1 locus as one conferring a high cross-race risk of development of type 2 diabetes and metabolic syndrome." (PMID 24367622, 2013). "Moreover, from a pathogenic point of view, overexpression of HMGA1 has been associated with human cancer, whereas functional variants of the HMGA1 gene have been recently linked to type 2 diabetes mellitus and metabolic syndrome." (PMID 24367622, 2013). "For example, reduced expression of the high mobility group A1 protein (HMGA1) associated with type 2 diabetes may be caused by upregulated transcription of the HMGA1p pseudogene, which competes with the 3′UTR of HMGA1 gene for the protein factor αCP1 critical for the stability of its mRNA." (PMID 34947885, 2021). "Within this metabolic context, novel HMGA1 molecular partners have been identified, and their functional interplay investigated, while, in the meantime, HMGA1 gene variants have been identified as reliably linked to both type 2 diabetes mellitus, and the metabolic syndrome." (PMID 30034366, 2018).
type 2 diabetes (continued). "Although our HMGA1 association analysis may be confounded if control patients eventually develop diabetes after study follow-up, the high mean age and lower mean BMI suggests that our control patients are less likely to develop type 2 diabetes." (PMID 23302499, 2013). "As it concerns HMGA1, on the basis of its involvement in insulin resistance, a role for this nuclear factor in type 2 diabetes has also been postulated and studies in this direction have been performed by us and others." (PMID 30034366, 2018). "Clinically, the importance of HMGA1 gene variability in glucose metabolism is emphasized in a wide range of clinical conditions ranging from rare insulin resistance syndromes to type 2 diabetes and the metabolic syndrome." (PMID 30034366, 2018). "Consistently with these observations, HMGA1 gene defects produce insulin resistance and type 2 diabetes in humans and mice, whereas protection against insulin resistance has been reported in transgenic mice overexpressing Hmga129." (PMID 29867121, 2018). "This group also described variants in the HMGA1 gene that associate in excess with type 2 diabetes however this association has been effectively refuted, so that a role for HMGA1 in human type 2 diabetes remains unsubstantiated." (PMID 28753127, 2017). "In particular, cardiac hypertrophy and type 2 diabetes were reported in Hmga1-null and heterozygous mice meaning that a correct quantity of HMGA1 protein is necessary for cardiomyocytic cell growth and regulation of the insulin pathway." (PMID 26895108, 2016). "For instance, post-transcriptional silencing of HMGA1 (MIM 600701) by its pseudogene (HMGA1-p) leads to insulin resistance and type 2 diabetes." (PMID 27506666, 2016). "Cardiac hypertrophy and type 2 diabetes were observed in Hmga1-null (A1-KO) and heterozygous mice suggesting that an appropriate amount of HMGA1 protein is required for cardiomyocytic cell growth and regulation of the insulin pathway." (PMID 24728959, 2014). "Because the HMGA1 protein participates in the regulation of the insulin receptor (INSR), the expression of HMGA1-p plays an important role in the onset of type 2 diabetes." (PMID 24312300, 2013). "Recently, the low frequency insertion polymorphism IVS5-13insC (c.136-14_136-13insC) in the high-mobility group A1 gene (HMGA1), a transcriptional regulator of the insulin receptor gene (INSR), was identified and associated with type 2 diabetes." (PMID 23302499, 2013). "Therefore, this study established a novel mechanistic linkage between HMGA1-p pseudogene expression and type 2 diabetes mellitus." (PMID 26895108, 2016). "Indeed, knock-out of the Hmga1 and Hmga2 genes leads to different phenotypes: cardiac hypertrophy and type 2 diabetes in the former case, and a large reduction in body size and amount of fat tissue in the latter case." (PMID 24728959, 2014). "Furthermore, rs9394200 is 5000 base pairs downstream from the of HMGA1 3′ end and is represented on arrays utilized by type 2 diabetes GWAS." (PMID 23302499, 2013). "As we previously reported, HMGA1 is a main activator of the INSR gene, and individuals with defects in HMGA1 have decreased INSR expression and increased susceptibility to type 2 diabetes mellitus." (PMID 24367622, 2013). "Inhibiting HMGA1 expression could offer new strategies for treating type 2 diabetes." (PMID 39507236, 2024). "In fact, the downregulation of HMGA1 protein leads to a reduced insulin receptor (INSR) expression in patients with insulin resistance and type 2 diabetes." (PMID 26895108, 2016). "Consistent with these latter findings, we have shown that defects in HMGA1 expression and/or function, by negatively affecting insulin receptor (INSR) signaling in insulin target tissues, may cause insulin resistance and increase susceptibility to type 2 diabetes mellitus." (PMID 24367622, 2013).
type 2 diabetes (continued). "In addition to its role in oncology and inflammation, HMGA1 was found to be involved in the transcription of insulin receptor INSR (as a sensor and regulator of insulin signaling), glucose homeostasis and therefore in type 2 diabetes development." (PMID 31762718, 2019). "Another noteworthy finding was the altered expression of the Hmga1 regulon in stressed mutant females, since a genetic lack of HMGA1 protein was reported to adversely affect insulin receptor (INSR) expression in cells and tissues in individuals with insulin resistance and type-2 diabetes." (PMID 37542675, 2023).